LPIN1 (lipin 1)
Diseases named in the same sentence as LPIN1 in open-access papers (continued):
Sharing a sentence is not in itself a finding about the gene and the disease.
cancer (14 papers, 2015 to 2025). A tumor composed of atypical neoplastic, often pleomorphic cells that invade other tissues. "Scd, Scd2, Dgat2, Fads2, Lpin1, Gpat3, Acaa2, Lpcat3, Pcyt2 and Pla2g4a have been reported to be closely associated with cancer." (PMID 35122680, 2022). "We observed that LPIN1 depletion mitigated gefitinib-induced LD production in drug-resistant cancer cells." (PMID 35565351, 2022). "This implies that LPIN1 is a key factor responsible for altered PKC activation in gefitinib-resistant cancer cells." (PMID 35565351, 2022). "The modulations of lipin-1 activity mediated by mTORC1 can affect mitochondria dynamics and regulate cancer." (PMID 33922580, 2021). "Via its enzymatic activity, lipin-1 was reported to promote several processes, including cell differentiation, inflammation and autophagy, which can contribute to both cancer initiation and progression." (PMID 33922580, 2021). "Taken together, these studies clearly show the pivotal role that lipin-1 can play in host cells to generate a favorable environment for cancer establishment and progression." (PMID 33922580, 2021). "We showed that IL-33 induced LPIN1 expression by regulating JNK/c-Jun signaling by activating the Cancer Osaka thyroid (COT)." (PMID 33946554, 2021). "Recent advances in understanding suggest that LPIN1 frequently observed in various human cancer cell lines controls the main cellular processes in cancer progression." (PMID 33946554, 2021). "More recently, it was reported that extracellular mechanical signals, which are altered in several cancer types, regulate lipid homeostasis via the direct modulation of lipin-1 enzymatic activity." (PMID 33922580, 2021). "Lipin-1 protein expression was detected in multiple cancer cell lines in this study, agreeing with at least one other study that showed lipin-1 expression in select cells." (PMID 33596934, 2021). "Lipin-1 has been found to be aberrantly upregulated in certain types of cancer cells, and its PAP activity is required for the survival of these cells." (PMID 33203880, 2020). "In a recent study, we observed that phenotypical modifications induced in cancer cells by lipin-1 silencing can be recapitulated by propranolol treatment." (PMID 29728578, 2018). "Most interestingly, lipin-1 depletion or lipins inhibition with propranolol sensitized cancer cells to rapamycin." (PMID 25834103, 2015). "Lpin1 can act as a transcriptional cofactor that regulates fatty acid oxidation and lipogenesis and is upregulated in certain types of cancer cells, and its activation of phosphatidic acid phosphatase is required for the survival of these cancer cells." (PMID 40941077, 2025). "Lipin-1 is known to regulate the lipid metabolism during fasting adaptation and appears critical for the survival of cancer cells; besides, it catalyzes a key step in the biosynthesis of triacylglycerol and phospholipids, which are essential for highly replicative cells." (PMID 37301960, 2023). "Several intracellular pathways regulated by lipin-1 are involved in cancer cell biology." (PMID 33922580, 2021). "The regulation of c-Jun is known to be an important event in various diseases, including cancer, but the influence of c-Jun on LPIN1 overexpression and its significance in oncogenesis remain unknown." (PMID 33946554, 2021). "Whatever the case may be, inhibition of HIF-1-dependent lipin-1 expression by CK1δ, appears to restrict cancer cell growth under hypoxia." (PMID 25744540, 2015). "As we observed that phosphorylation of AKT and ribosomal protein S6 were decreased following lipin-1 silencing, we hypothesized that lipin-1 silencing could potentiate the anti-proliferative effect of rapamycin on cancer cells." (PMID 25834103, 2015).
cancer (continued). "As Rac1 is frequently over-expressed or over-activated in cancers, we reasoned that lipin-1 might also be over-expressed in various cancer cell lines as compared to normal skin fibroblasts or endothelial cells." (PMID 25834103, 2015). "This study demonstrates for the first time that the targeting of lipin-1 is a potential new anti-cancer strategy that could be used alone or in combination with drugs like rapamycin." (PMID 25834103, 2015). "Lipin-1 depletion also decreased cancer cell migration through RhoA activation." (PMID 25834103, 2015). "In addition, lipin-1 depletion strongly inhibited cancer cells proliferation while it had only limited effect on non-cancerous cells." (PMID 25834103, 2015). "It is also important to underline that mTORC1 can phosphorylate lipin-1 on multiple sites, and that these sequential phosphorylations target lipin-1 to the ER membrane, which, due to the proximity to its substrate, enhances its PAP activity and promotes cancer growth." (PMID 33922580, 2021). "However, lipin-1 also regulates cancer cell phenotype through other signaling pathways." (PMID 33922580, 2021). "Our results also demonstrated that cancer cells acquire resistance to gefitinib by increasing DAG, which is produced by LPIN1." (PMID 35565351, 2022). "Inhibition of CK1δ increases lipid droplet formation and proliferation of both cancer and normal cells specifically under hypoxia and in an HIF-1α- and lipin-1-dependent manner." (PMID 25744540, 2015). "To validate the PKCδ-mediated function of LPIN1 in gefitinib resistance, we investigated two downstream effects of PKC function, NF-κB signaling and lipogenesis, which play important roles in tumorigenesis and drug resistance by providing pro-survival signals to cancer cells." (PMID 35565351, 2022). "Therefore, LPIN1-mediated DAG production is important to acquire gefitinib resistance in H1650 cells, and blocking LPIN1 and PLC simultaneously may be effective in treating drug-resistant cancers." (PMID 35565351, 2022). "Hence, due to its central role in lipid homeostasis, it is not surprising that lipin-1 was recently identified as a regulator of cancer progression." (PMID 33922580, 2021). "Lipin-1 KD decreased both PCa cell proliferation and migration through RhoA activation, increased PA levels, and induced autophagy through the inhibition of PI3K/AKT/mTORC1 pathway., Lipin-1 depletion with propranolol sensitized cancer cells to rapamycin, suggesting new combination therapies." (PMID 34386430, 2021). "In addition, LPIN1 depletion has been shown to strongly inhibit the proliferation of cancer cells, with only a limited effect on non-cancerous cells." (PMID 33946554, 2021). "In addition, interestingly, lipogenic genes, including SREBFs, ACLY and FASN, were reduced by LPIN1 knockdown, suggesting that LPIN1 is not a passive lipogenic gene but a driver gene that actively induces alterations in lipid metabolism in TKI-resistant cancer cells." (PMID 35565351, 2022).
myopathy (11 papers, 2019 to 2025). A disease of the muscle in which the muscle fibers do not function properly. "Previously, Jama et. al.48 generated conditional knockout mice Lpin1Myf5cKO and found that LPIN1 deficiency induced reduced muscle mass and myopathy." (PMID 33456573, 2021). "Work conducted with fld and skeletal muscle–specific Lpin1-KO mice has revealed that loss of lipin 1 in muscle of mice leads to active and ongoing myopathy that is secondary to impairments in autophagy." (PMID 33986192, 2021). "Patients with a genetic defect causing loss of function of LPIN1 (gene coding for LIPIN 1) develop myopathy, affecting both skeletal muscle and the heart." (PMID 34360941, 2021). "A heterozygous carrier of a predicted pathogenic mutation in LPIN1 was responsible for statin‐induced myopathy." (PMID 31617323, 2019). "Of these, heterozygous LPIN1 missense mutations can facilitate myopathy induced by statins." (PMID 37964368, 2023). "Additionally, they revealed the mechanism behind myopathy induced by attenuated lipin 1 activity in response to statin therapy and identified the specific intersection of lipin 1 deficiency and statin pharmacodynamics." (PMID 37964368, 2023). "We have recently shown that deletion of lipin 1 in skeletal muscle of mice impairs autophagy and accumulation of abnormal mitochondria, and it produces active myopathy, including loss of skeletal myocytes to necrotic cell death, macrophage infiltration, and sterile inflammation of muscle." (PMID 33986192, 2021). "Thus, altered levels of lipin-1 affects the energy metabolism, mitochondrial enzymes the glycolysis, glycogenolysis, and mitochondrial respiration, which leads to impaired skeletal muscle functions causing severe myopathies." (PMID 33673200, 2021). "The myopathy observed in lipin 1–deficient skeletal myocytes was also not observed in cardiac myocytes." (PMID 33986192, 2021). "A previous study demonstrated a severe myopathy after deletion of lipin-1 in murine model skeletal muscle, and an increased phospholipid biosynthesis of PC, PE, PI, and PG, thus providing a tool for assessing lipin-1 role on skeletal muscle function and metabolism." (PMID 33673200, 2021).
metabolic disease (7 papers, 2013 to 2026). A congenital disorder (due to inherited enzyme abnormality) or acquired (due to failure of a metabolically important organ) disorder resulting from an abnormal metabolic process. "LPIN1-related acute recurrent rhabdomyolysis (RM), first reported in 2008, is an autosomal recessive inherited metabolic disease." (PMID 33514355, 2021).
peripheral neuropathy (7 papers, 2008 to 2024). A disorder affecting the peripheral nervous system. "We also evaluated a genetic model of generalized peripheral neuropathy, the Lpin1–/– (lipin 1–deficient) mouse, which exhibits impaired peripheral nerve function due to alterations in Schwann cell lipid synthesis." (PMID 36180720, 2022). "Lpin1 null mutations also lead to peripheral neuropathy due to the dysregulation of a battery of genes required for the regulation of storage lipid metabolism in both the endoneurium and peri/epineurium." (PMID 19936100, 2008). "Whether and how lipin 1 deficiency in humans leads to peripheral neuropathy is yet unclear." (PMID 33456573, 2021). "Moreover, it remains elusive whether lipin 1 deficiency in human adults would cause peripheral neuropathy as in the mouse model." (PMID 33456573, 2021).
infection (4 papers, 2018 to 2025). The state of being infected such as from the introduction of a foreign agent such as serum, vaccine, antigenic substance or organism. "Meanwhile, after 2 days post-infection, Med17 overexpression (Med17-oe) led to the significant downregulation of adipogenesis-related genes, including Fasn, Scd1, Elovl6, and Lpin1 (p < 0.05)." (PMID 41199171, 2025). "After precipitation with anti-PPARγ antibody, the quantitative analysis showed that compared with the 0-h non-infection group, the amount of precipitated Acc, Adipoq and Lpin1 after 48 h of Ad36 induction increased by 8.99, 7.86, and 2.10 folds, respectively." (PMID 30902099, 2019). "As expected from our previous study, infection of lipin-1 deficient cells with HCV or VSVpp resulted in normal entry." (PMID 31752156, 2019).
liver (4 papers, 2008 to 2023). "Lpin1 fatty liver dystrophic (fld) mice, i.e., Lpin1(fld/fld)-deficient mice, carrying spontaneous inactivating mutations in the Lpin1 gene, show the characteristic features of the human congenital lipodystrophy." (PMID 28986436, 2017).
cardiovascular disease (2 papers, 2020 to 2023). "Lack of Lpin1 can lead to severe metabolic homeostasis, such as fatty liver and cardiovascular disease." (PMID 31949263, 2020).
neurological disorders (2 papers, 2021 to 2022). "Moreover, we identified 3 upregulated [ENO3, LPIN1 and SCN9A] and 3 downregulated [ATL3, CPT1C, and SGCB] RNAs whose genes have been implicated in neurological disorders." (PMID 34907471, 2022).
genetic peripheral neuropathy (1 paper, 2022). "Conversely, genetic peripheral neuropathy resulting from lipin 1 deficiency led to a marked reduction to all three parameters." (PMID 36180720, 2022).
LPIN1 also shares sentences with these, for which no sentence is quoted: Abdominal obesity (2 papers); muscle disorders (2); neuropathies (2); pancreatic cancer (2); acute lymphoblastic leukemia (1); acute myeloid leukemia (1); adenocarcinoma (1); Adult onset (1); Alport syndrome (1); breast adenocarcinoma (1); cardiomyopathy (1); Childhood onset (1); congenital myopathies (1); demyelination (1); diabetic encephalopathy (1); diabetic nephropathy (1); Duchenne muscular dystrophy (1); dyslipidaemia (1); gastric cancer (1); glucose metabolism disorder (1); hepatoblastoma (1); hereditary hemochromatosis (1); homocysteinemia (1); Huntington disease (1); Hypercholesterolemia (1); Hyperglycemia (1); hyperlipidemia (1); Impaired glucose tolerance (1); Infertility (1); Long QT syndrome (1).
A further 18 diseases each share a sentence with LPIN1 in 1 paper.